IL10 (interleukin 10)
Diseases named in the same sentence as IL10 in open-access papers (continued):
Sharing a sentence is not in itself a finding about the gene and the disease.
depression (continued). "Notably, individuals who have high stress-induced IFN-γ versus negative immunoregulatory cytokines, such as IL-10, experience significantly increased symptoms of stress-induced anxiety and depression compared to subjects with higher IL-10 expression." (PMID 38791125, 2024). "However, the role of the anti-inflammatory cytokine IL-10 in chronic-stress-induced depression is not as straightforward as the proinflammatory cytokines discussed previously." (PMID 38791125, 2024). "Although we cannot confirm whether DEX-dam represents postpartum depression/anxiety in humans, we propose the possible involvement of microglia and circulating IL-10 in postpartum depression/anxiety rather than neurons and other glial cells." (PMID 37396924, 2023). "Clinical studies have found that compared with normal people, patients with depression have proinflammatory cytokines such as tumor necrosis factor-α(TNF-α)、Interleukin-1β(IL-1β)、IL-6 and interferon While anti-inflammatory cytokines such as IL-10, IL-4, IL-8 and transforming growth factor." (PMID 37167313, 2023). "Patients with depression disorder exhibit a chronic inflammatory state which is characterized by elevated serum levels of pro-inflammatory cytokines, including TNF-α, IL-1β, IL-2, IL-6, IL-12, and decreased levels of anti-inflammatory cytokines, such as IL-10, compared to controls." (PMID 37273278, 2023). "first reported the association of cytokine polymorphisms with PSD, showing that patients with polymorphisms of anti-inflammatory cytokines IL-4 and IL-10 rather than pro-inflammatory cytokines TNF-α, IL-1β, IL-6 and IL-8 had an increased propensity to develop depression in the acute phase of stroke." (PMID 36225923, 2022). "Moreover, since CBD significantly decreases IL-10 production, we may conclude that treatments with CBD concentrations ranging from 1.0–1.0 μg/mL should be avoided in depression and probably in most immune and autoimmune disorders." (PMID 35455402, 2022). "However, it should be stressed that the master regulatory cytokine IL-10 was not significantly higher in depression versus controls indicating that those CIRS functions are insufficient to damp IRS activation." (PMID 35455402, 2022). "Interestingly, during a one- year study-period, serum levels of IL-6, IL-10, TNF-α, and IFN-γ were significantly higher in the post-stroke depression group relative to a control group, suggesting a relationship between immune dysregulation and post-stroke depression." (PMID 34884906, 2021). "More precisely, MDD had increased IL-1β, tumor necrosis factor α (TNF α), sTNFR 1, IL-12 and IL-10 while BD depression was characterised by an increase in IL-6, sTNFR 2, IL-18, IL-33, ST2, and KLOTHO." (PMID 33946871, 2021). "Previous meta-analyses have suggested that not only pro-inflammatory cytokines but also IL-10, an anti-inflammatory cytokine, are significantly elevated in MDD patients compared to those in healthy controls, which indicates that a more complicated mechanism is involved in depression." (PMID 32699226, 2020). "In addition, IL-10 decreased in mPFC and BA, while IL-1β and TNF-α protein expression increased in mPFC, BA, and VH on POD 45, which indicated a CNS shift to pro-inflammatory profile at the time when anxiety- and depression-related behaviors were observed." (PMID 30208926, 2018). "However, Karaoulanis and colleagues found that serum levels of three cytokines (IL-6, TNF-α, and IL-10) did not significantly change in relation to hot flashes in perimenopausal women with depression." (PMID 28846735, 2017). "The data revealed significant differences between our groups, F = 4.88, p = .01, η2 = .15, but the reduction in IL10 induction was restricted to hip fracture patients with depressive symptoms compared with healthy controls, p = .04 and hip fracture patients without depression, p = .01." (PMID 26112234, 2016).
depression (continued). "Furthermore, the present study found that Th17/Treg ratio was negatively correlated with levels of IL-10 but not correlated with anxiety, depression, or stroke severity." (PMID 26166952, 2015). "A correlation analysis of the Hospital Anxiety and Depression Scale score and cytokine levels revealed positive associations with the domain of anxiety/depression with IL-6, IL-1beta and TNF-alpha and a negative correlation with IL-10." (PMID 26300773, 2015). "Furthermore, immunohistochemistry revealed significant differences in the positive expression of IL-1β and IL-10 between the anxiety-depression and non-anxiety-depression IBS-D groups." (PMID 23935726, 2013). "Finally, as expected based on a cytokine perspective of the disorder, depression during IFN-α treatment was most likely to be instigated among those individuals with the highest baseline levels of soluble IL-2 receptor (sIL-2r), IL-6, and IL-10." (PMID 23675319, 2013). "However, the proportion of IL-10-positive cells in the anxiety-depression IBS-D group (0.075±0.097) was significantly lower than that in the non-anxiety-depression IBS-D group (0.104±0.257; P<0.05)." (PMID 23935726, 2013). "Furthermore, increased IL-10 level does not always reflect depression disease severity or suicide, suggesting that it may not always act as a compensatory mechanism." (PMID 40179065, 2025). "Lower levels of IL-10 have been shown in depressed patients who died by suicide, but suicidal behaviour in patients with schizophrenia spectrum disorder may not be directly comparable to suicidal behaviour in depression per se." (PMID 38549611, 2024). "IL-10 levels were not significantly different between both groups at any condition and there was a trend towards higher levels in the control, 0.1 and 1.0 μg/mL conditions, whilst there was a trend towards lowered levels in the 10.0 μg/mL condition in depression as compared with controls." (PMID 35455402, 2022). "In fact, it is admissible that the absence of IL-10, in IL-10KO mice, leads to an increased production of proinflammatory cytokines that could, in accordance with the “cytokine theory of depression”, trigger depression." (PMID 19936104, 2009). "The difference between IL-6 and IL-10 levels in women with and without HDRS score-based depression was not statistically significant." (PMID 37840785, 2023). "Exosomal IL-10 levels are related to PTSD symptoms (B = 0.8, t = 2.60, p < 0.01).IL-10 regression model (p < 0.01) shows PTSD sig. related (p < 0.01) and depression (p = 0.063) and PCS severity do not relate to exosomal IL-10 (p = 0.26)." (PMID 37251220, 2023). "The difference between IL-6 and IL-10 levels in women with and without EPDS score-based depression was not statistically significant." (PMID 37840785, 2023). "In the absence of a head injury, the relation between IL-10 and psychological outcomes, PTSD, and depression is inconclusive." (PMID 35053845, 2022). "At the same time, the percentages of IL-10-producing and FoxP3-expressing CD4+ T-cells (with CD3/CD28-stimulation) was higher in MS patients without depression." (PMID 36189272, 2022). "Neither the logIC IL-6, logEC IL-10, and logIC TNF-α values at baseline, follow-up, nor their overall courses significantly correlated with depression severity scores or course measured by the BDI-II or the HAMD (data not shown)." (PMID 33447872, 2021). "The correlation with the reduction of depression symptomatology we observed for TNF-α, IL-6, and IL-10 levels is not fully consistent with the reported alterations of these cytokines after antidepressant treatment according to most recent meta-analyses." (PMID 31375659, 2019). "Other studies have not found any correlations between L-6, IL-8, IL-10, TNF-α, FIQ and depression, IL-6 and depression or anxiety, IL-6 and pain score, FIQ, or TNF-α." (PMID 29849487, 2018).
depression (continued). "These meta-analyses showed additionally that Th2 and Tregulatory (Treg) cytokines (including IL-10, IL4, and IL-5) were not significantly altered in major depression indicating that major depression is characterized by M1 and Th1 activation." (PMID 29103192, 2018). "Rats with depression-like phenotype displayed increased levels of cytokines (IL-1β, IL-6, TNF-α, IL-4 and IL-10) in the PFC compared with sham-operated and rats without depression-like phenotype (P < 0.05) on day 21 after SNI surgery." (PMID 28600519, 2017). "Thus, in human depression and animal models of depression antidepressants, such as tricyclics and SSRIs, suppress the production of interferon (IFN)-γ and interleukin (IL)-1β and increase the production of IL-10, a negative immunoregulatory cytokine." (PMID 37409130, 2023).
breast cancer (320 papers, 2002 to 2026). A primary or metastatic malignant neoplasm involving the breast. "MDSCs and tumor-associated platelets (TAPs) further contribute to breast cancer immune evasion by inhibiting T-cell and NK-cell activity, secreting immunosuppressive cytokines such as IL-10 and TGF-β, and promoting regulatory T-cell expansion." (PMID 41348261, 2025). "Breast cancer-associated MDSCs increase the expression of PD-L1 and release cytokines such as IL-10 and TGF-β." (PMID 41550427, 2025). "IL-10 is generally considered an immunosuppressive cytokine and is associated with poor prognosis in breast cancer." (PMID 40909271, 2025). "Clinical studies in patients with breast cancer before chemotherapy have reported that higher circulating levels of IL-4 and IL-10 are associated with better cognitive performance, particularly in attention and processing speed tasks." (PMID 41155372, 2025). "This prognostic trend is corroborated by our meta-analysis, which demonstrated a consistent association between elevated IL-10 levels and significantly poorer survival across breast cancer cohorts." (PMID 41007766, 2025). "It increases considerably in breast cancer tissues and exhibits a strong association with lymphovascular infiltration and interleukin 10 (IL‐10) expression." (PMID 39382373, 2024). "One study on the Indian population12and one on the Italian population13found that the low IL-10 expressing AA genotype is associated with higher breast cancer risk." (PMID 37501757, 2023). "So, IL-10 is a cytokine to be avoided in a tumor microenvironment because it is associated with a bad prognosis for any type of cancer, including breast cancer." (PMID 37283734, 2023). "On the other hand, breast cancer drug resistance can occur after enchantment of IL-10 secretion by tumor-associated macrophages." (PMID 36544523, 2022). "Fully adjusted-models showed a significant positive association with breast cancer risk with levels of IL-10 in premenopausal women [OR1SD = 1.20 (1.03–1.41)]." (PMID 35430795, 2022). "Moghimi and other authors found that there was a significant association between the IL-10 rs1800872 polymorphism and risk of breast cancer under four genetic models: allele, homozygote, dominant, and recessive." (PMID 36009467, 2022). "It was found that large amount of IL-10 secreted by tumor-associated macrophages (TAMs) contributed to breast cancer drug resistance." (PMID 33717103, 2021). "A previous study on MDA-MB-231 and MCF-7 cell lines show that IL-6 and IL-10 are associated with good prognosis in breast cancer." (PMID 32560316, 2020). "In the current study, we aimed to evaluate the association between single nucleotide polymorphisms (SNPs) of interleukin-10 (IL-10) and susceptibility to breast cancer in Shaanxi Han women in China." (PMID 32380517, 2020). "Here, we genotyped six SNPs (rs1554286, rs1518111, rs3021094, rs3790622, rs3024490, rs1800871) of IL-10 genes in a case-control study to explore the association between polymorphisms of IL-10 and the risk of breast cancer in Northwest Chinese Han women." (PMID 32380517, 2020). "Immunoregulatory cytokines, such as IL10, are important actors in tumor microenvironment associated with breast cancer." (PMID 32300557, 2020). "A systematic review and meta-analysis revealed that the rs1800871 and rs1800872 polymorphisms of the IL-10 gene are associated with overall breast cancer risk in the general population." (PMID 33003428, 2020). "Overexpression of IL-10 has been shown to confer tumor growth and is associated with poor prognosis in breast cancer, highlighting the tumorigenic properties of IL-10." (PMID 32222879, 2020). "Our data shed new light on the association between IL-10 SNPs and breast cancer susceptibility in Shaanxi Han women in China." (PMID 32380517, 2020).
breast cancer (continued). "TAMs and its supernatants significantly prevent breast tumor cells from apoptosis caused by paclitaxel and the high level of IL-10 secreted by TAMs was responsible for drug resistance of breast cancer." (PMID 30175384, 2018). "High levels of expression of IL-10 and IL-17 in breast cancer following NAC have been shown to be significantly associated with failure to achieve a pCR." (PMID 29390966, 2018). "Some investigators found genetic evidence for association between IL10 -1082A > G, −819 T > C, −592A > C and TNFα -308G > A polymorphisms and breast cancer progression in different ethnic populations." (PMID 26112140, 2015). "Holders of IL10 -592A > C heterozygous IL10 -592 AC genotype had a higher probability of estrogen receptor positive breast cancer phenotype than homozygous variants (P = 0.017)." (PMID 26112140, 2015). "In this prospective cohort study of 100 premenopausal female patients with early-stage breast cancer, we investigated associations between functional SNPs in IL10 and TNFα genes, previously implicated in breast cancer occurrence, spread and survival." (PMID 26112140, 2015). "In this study, we found IL-10 expression was not only associated with advanced stage and lymph node metastasis in human primary breast cancer tissues, but also significantly correlated with ILT4 expression (r = 0.577; p < 0.01)." (PMID 24762057, 2014). "IL10 variant genotype was associated with increased breast cancer risk in all three types of breast cancers." (PMID 25559835, 2014). "Our data demonstrated the association of ILT4 and IL-10 expression in human breast cancer, suggesting their important roles in immune dysfunction and lymph node metastases." (PMID 24762057, 2014). "Our study further demonstrated that ILT4 overexpression in breast cancer was associated with the overexpression of IL-10." (PMID 24762057, 2014). "It has been demonstrated that polymorphisms of the IL-10 gene are associated with multiple cancer, such as gastric cancer, non-small cell lung cancer and breast cancer, and our results indicating that the polymorphisms of IL-10 are associated with GBM." (PMID 23663500, 2013). "In this study, immunohistochemical stromal expression of COX-2, TGF-β, IL-10 and Ki67 was associated to breast cancer mortality." (PMID 22353218, 2012). "High stromal expression of COX-2 and Ki67 in metastases, as well as high stromal expression of TGF-β and IL-10 in primary tumors were independently associated to breast cancer mortality." (PMID 22353218, 2012). "It has been reported that IL-10 gene SNP was associated with several diseases such as breast cancer, cervical cancer, multiple myeloma, and gastric carcinoma." (PMID 22690243, 2012). "In this case-control study we evaluated the association between the polymorphisms of the IL-10 promoter and breast cancer in a Han Chinese population." (PMID 20553628, 2010). "Although several studies have shown the possible involvement of IL-10 in the pathogenesis of breast cancer, as well as its association with prognosis in different ethnic populations, the results were not all consistent." (PMID 20553628, 2010). "In conclusion, in this case-control study, we report for the first time that the IL-10 promoter polymorphisms were significantly associated with the prognostic and predictive factors of breast cancer in a Chinese han population." (PMID 20553628, 2010). "The aim of this study was to evaluate any role of specific SNPs in the interleukin genes IL1A, IL1B, IL1RN, IL4R, IL6 and IL10 in predisposition to breast cancer susceptibility and severity." (PMID 16842617, 2006). "Interestingly, IL-10-producing Bregs in TLS-like aggregates in breast cancer patients are associated with shorter metastasis-free survival." (PMID 40321752, 2025).